ASCL3 (achaete-scute family bHLH transcription factor 3)
Description:
Transcriptional repressor. Inhibits myogenesis. Plays a role in progenitor cells which differentiate into ductal and acinar, but not myoepithelial, cell lineages in the salivary glands. Involved in the functions of the microvillar cells and Bowman's glands and probably, in a non-cell-autonomous manner, in the development or regeneration of a complete olfactory epithelium (OE).
Synonyms: hASH3; bHLHa42; SGN1
Tractability: No criterion of Open Targets' tractability assessment is met for any kind of drug.
Gene: Protein-coding gene on chromosome 11 (8,937,578 to 8,943,016, reverse strand). Ensembl gene ENSG00000176009.
Subcellular location: Nucleus
Gene Ontology:
Molecular function: protein binding; DNA binding; DNA-binding transcription factor activity, RNA polymerase II-specific; RNA polymerase II transcription regulatory region sequence-specific DNA binding; DNA-binding transcription repressor activity, RNA polymerase II-specific; protein dimerization activity
Biological process: positive regulation of transcription by RNA polymerase II; regulation of transcription by RNA polymerase II; animal organ development; epithelium development; negative regulation of transcription by RNA polymerase II; salivary gland development; sensory epithelium regeneration; tissue homeostasis
Cellular component: chromatin; RNA polymerase II transcription regulator complex; nucleus; transcription regulator complex
Genetic constraint (gnomAD): Loss-of-function variants: 4 observed, 5.92 expected, observed/expected ratio (o/e) 0.68, 90% interval 0.33 to 1.5. That is too few expected variants to judge how well the gene tolerates losing a copy. Missense variants: 243 observed, 241.2 expected, observed/expected ratio (o/e) 1.01, 90% interval 0.91 to 1.12. Synonymous variants: 98 observed, 93.5 expected, observed/expected ratio (o/e) 1.05, 90% interval 0.89 to 1.24.
Homologues: Orthologues: chimpanzee ASCL3 (98% identical), macaque ASCL3 (94% identical), guinea pig ASCL3 (77% identical), rabbit ASCL3 (75% identical), rat Tmem9b (66% identical), mouse Ascl3 (65% identical), tropical clawed frog ASCL3 (38% identical), Drosophila melanogaster ase (23% identical), zebrafish ascl1a (23% identical), Drosophila melanogaster ac (18% identical). Paralogues in human: ASCL5 (35% identical), ASCL4 (31% identical), ASCL1 (24% identical), ASCL2 (23% identical).
Diseases named in the same sentence as ASCL3 in open-access papers:
ASCL3 is named in the same sentence as 11 diseases in open-access papers, as found by Europe PMC text mining. Sharing a sentence is not in itself a finding about the gene and the disease. The quoted sentences say what the papers report.
asthma (2 papers, 2025). "Expression of known ionocyte markers FOXI1, ASCL3, PDE1C, TFCP2L1 and CFTR in single cells was lost in hBECs from patients with neutrophilic asthma (and reduced in paucigranulocytic asthma) compared to healthy donors or eosinophilic asthma." (PMID 39358991, 2025).
brain tumor (1 paper, 2009). "Among those genes are ASCL2 and ASCL3, mammalian homologues of Drosophila achaete-scute complex, as well as TRIM3, a homologue of Drosophila brain tumor involved in progenitor cell proliferation control and cancer stem cell suppression, and a cluster of more distantly related TRIM genes." (PMID 19250537, 2009).
breast carcinoma (1 paper, 2022). "ASCL3 is overexpressed in breast cancer (Hanahan,Weinberg, 2011) but is underexpressed (relative to normalcontrols) in kidney, cervical, and bladder cancers as well aslymphoma and melanoma." (PMID 35774364, 2022). "For example, ASCL3 is overexpressed in breast cancer, and NOS1, in ovarian cancer cell lines." (PMID 35774364, 2022).
cystic fibrosis (1 paper, 2020). Autosomal recessive disorder caused by pathogenic variants in the CFTR gene (cystic fibrosis transmembrane conductance regulator), which encodes a chloride and bicarbonate channel expressed in epithelial cells, and follow the diagnosis criteria. "Like ionocytes in mouse airways and human LAE, the human SAE ionocytes highly expressed the transcription factors FOXI1 and ASCL3, V-ATPase-subunit genes (ATP6V1G3, ATP6V0B), and the Cl− ion channel CFTR, that when mutated, causes cystic fibrosis." (PMID 32727470, 2020).
glioma (1 paper, 2009). A benign or malignant brain and spinal cord tumor that arises from glial cells (astrocytes, oligodendrocytes, ependymal cells). "Thus, our results rule out ASCL2 and ASCL3 and the more distantly related TRIM genes as potential glioma tumor suppressors within the genomic region analyzed." (PMID 19250537, 2009).
kidney cancer (1 paper, 2022). Primary or metastatic malignant neoplasm involving the kidney. "Our experimental results are consistent withthe literature showing GRIN1 underexpression in schizophrenic disorders as well as an increased risk of cervical,bladder, and kidney cancers and lymphoma during ASCL3 underexpression." (PMID 35774364, 2022).
tumor (3 papers, 2009 to 2021). "In particular, this included genes involved in secretory pathways, lipid and sugar metabolism (such as, UGDH, SORD, GLUD1, ELOVL5, ASCL3, UAP1), but also genes implicated in tumor progression and metastasis with functions in cell survival, proliferation and adhesion (EHF, ELL2, TPD52, MAFB, SGK)." (PMID 21829708, 2011). "As ferroptosis plays crucial roles in both immunity and pulmonary carcinogenesis, the correlation between CISD1, FANCD2, PGD, ASCL3, ATP5MC3, and SLC7A11 expression and tumor immune infiltration in LUAD was evaluated utilizing data obtained from the TIMER database." (PMID 35320929, 2021).
genetic disorders (1 paper, 2025). "Among the prioritized custom CMA genes in the smallest custom CMA NDDi, KIAA1586, ASCL3, BTNL3, SIRPB1, and GLT1D1 exhibit high average shortest path length and low proximity, indicating vulnerability to genetic disorders." (PMID 40869915, 2025).
ASCL3 also shares sentences with these, for which no sentence is quoted: cancer (2 papers); lymphoma (1); ovarian carcinoma (1).